PDK4 (pyruvate dehydrogenase kinase 4)
Diseases named in the same sentence as PDK4 in open-access papers (continued):
Sharing a sentence is not in itself a finding about the gene and the disease.
breast cancer (31 papers, 2012 to 2025). A primary or metastatic malignant neoplasm involving the breast. "Previous report has mentioned that PDK4 is overexpressed in breast cancer cells and associated with poor patient outcomes." (PMID 38678126, 2024). "In this study, we identified 8 cDEGs (COL11A1, COL10A1, CD36, ACACB, CD24, PLK1, UBE2C, and PDK4) as breast cancer (BC)-causing HubGs from 3 microarrays and one scRNA-seq dataset by the protein-protein interaction (PPI) network analysis of 46 cDEGs." (PMID 37893423, 2023). "High PDK4 is associated with poor survival in breast cancer and increased cell growth in bladder cancer cell lines." (PMID 32323921, 2020). "Our current study demonstrate that genes involved in myogenesis (i.e., Pax7 and Myod) and muscle function (i.e., Myh1 and Pdk4), as well as miR-486, a regulator of myogenesis, are uniquely dysregulated in skeletal muscles based on breast cancer subtype and mutation pattern." (PMID 38651826, 2024). "Further, clinical data confirm that m6A/PDK4 is implicated in breast cancer progression." (PMID 35186927, 2022). "PDK4 is decreased in a variety of cancers, such as gastric cancer, prostate cancer, breast cancer, lung cancer and liver cancer, and may be associated with the inhibition of cell proliferation and induction of apoptosis." (PMID 36338978, 2022). "In hepatocellular carcinoma downregulation of PDK4 is associated with poor prognosis, and PDK4 downregulation in lung cancer promoted cell proliferation and tumor growth, while high PDK4 expression was correlated with poor patient outcome in breast cancer." (PMID 33014872, 2020). "Our observation is consistent with previous reports in the literature, which showed PDK4-mediated inhibition of autophagy in vascular smooth muscle cells and breast cancer cells." (PMID 40626362, 2025). "Pyruvate dehydrogenase kinase isozyme 4 (PDK4) has been denoted as a determinant of breast cancer metabolism." (PMID 38678126, 2024). "Before investigating the role of PDK4 in breast cancer, PDK4 expression in breast cancer cells was examined using RT-qPCR and western blotting." (PMID 38678126, 2024). "The target of this study was to untangle the functional mechanism of PDK4 in ferroptosis dependent on autophagy in breast cancer." (PMID 38678126, 2024). "All these findings hinted the promoting role of PDK4 inhibition in the autophagy in breast cancer cells." (PMID 38678126, 2024). "Knockdown of PDK4 induced the autophagy of breast cancer cells and 3-methyladenine (3-MA), an autophagy inhibitor, countervailed the promoting role of PDK4 interference in ferroptosis in breast cancer cells." (PMID 38678126, 2024). "Considering the overexpression of PDK4 in breast cancer, PDK4 was then knocked down in MCF-7 cells in the following functional experiments." (PMID 38678126, 2024). "Consistently, increased PDK4 expression in breast cancer cells was also confirmed in our present work." (PMID 38678126, 2024). "Nonetheless, the impacts of PDK4 on the autophagy and ferroptosis of breast cancer cells are indistinct." (PMID 38678126, 2024). "With the goal of substantiating the involvement of ASK1/JNK signaling in PDK4-mediated autophagy-dependent ferroptosis in breast cancer cells, ASK1 inhibitor GS-4997 was also utilized." (PMID 38678126, 2024). "The distinct pathological properties of PDK4 in PCa were subsequently reproduced by an extended study involving clinical cohorts of human patients with breast cancer (BCa)." (PMID 37903887, 2023). "We selected basally regulated genes (CCND1, PDK4, GREB1) encoding critical regulators of breast cancer progression, and performed RT-qPCRs in unstimulated T47D cells." (PMID 36076907, 2022). "In Breast Cancer (BC), METTL3 overexpression enhanced the PDK4 protein expression in breast cancer cells." (PMID 35186927, 2022). "PDK4 are highly up regulated in various cancers including glioblastoma, lung carcinoma, pancreatic cancer and breast cancer." (PMID 34777466, 2021).
breast cancer (continued). "PDK4 acts as a potential tumor suppressor because its expression is significantly reduced in lung, ovarian, colon and breast cancers." (PMID 34517344, 2021). "PDK4 has been described as a critical mediator of EMT and associated with antiestrogen resistance in human breast cancer." (PMID 32699630, 2020). "Perhaps the most intriguing finding from our study was that CL-TNBC, specifically, had much higher expression of CD36, LPL, PDGFRB, FABP4, and PDK4 compared to all other breast cancers, including basal-TNBC." (PMID 31942031, 2020). "By simply dividing patients in upper and lower quartiles and using a database with more cases, we observed a positive correlation of PDK4 expression with survival in breast cancer patients." (PMID 33014872, 2020). "Based on our findings, we proposed a novel anti-breast cancer mechanism mediated by PDK4." (PMID 38678126, 2024). "Mechanistically, activation of ASK1/JNK signaling mediated by PDK4 silence might promote autophagy-dependent ferroptosis in breast cancer cells." (PMID 38678126, 2024). "Accordingly, whether PDK4 functioned in the ferroptosis and autophagy in breast cancer cells via mediating ASK1/JNK pathway was the focus of our present work." (PMID 38678126, 2024). "Briefly, our findings supported the speculation that PDK4 might inactivate ASK1/JNK signaling to suppress autophagy-dependent ferroptosis in breast cancer." (PMID 38678126, 2024). "Functionally, silencing of PDK4 induced autophagy and ferroptosis in breast cancer cells." (PMID 38678126, 2024). "Taken together, inhibition of PDK4 might activate ASK1/JNK signaling to promote autophagy-dependent ferroptosis in breast cancer cells." (PMID 38678126, 2024). "RT-qPCR and western blotting examined PDK4 mRNA and protein levels in breast cancer cells." (PMID 38678126, 2024). "In addition, patients with breast cancer and high PDK4 expression have poor prognosis and survival rates." (PMID 36362028, 2022). "PDK4 is reported to be involved in diverse cancers, such as colon, lung, and breast cancers." (PMID 36362028, 2022). "Additionally, PDK4 alters regulation of PDH and is associated with antiestrogen resistance in breast cancer." (PMID 36059650, 2022). "Previous reports had revealed that upregulating PDK4 could affect numerous carcinomas, such as lung carcinoma, breast carcinoma, ovarian carcinoma, and colon carcinoma." (PMID 34220962, 2021). "PDK4 on the contrary was connected to poor patient outcome in breast cancer." (PMID 33014872, 2020). "Similarly, cholesterol-mediated increase in PDK4 is of significant interest in this regard, as it is also a key enzyme in glucose and fatty acid metabolism, and its expression is upregulated in breast cancer and correlates with poor patient outcomes." (PMID 32717915, 2020). "The role of PDK4 in cancer therapy is complex; the inhibition of PDK4 is sufficient to inhibit the proliferation of and induce apoptosis in lung cancer cells, but the overexpression of PDK4 is also able to decrease ATP levels and suppress de novo lipogenesis and proliferation in breast cancer cells." (PMID 24376596, 2013). "However, recent studies have also demonstrated that overexpression of PDK4 is sufficient to inhibit proliferation of breast cancer cells and that PDK4 expression is downregulated in a number of different cancer tissues." (PMID 22911820, 2012). "At the same time, through western blotting, the down-regulation of PDK4 was intriguingly noted to enhance the phosphorylated protein levels of ASK1 and JNK in MCF-7 cells, implying that PDK4 silence might function as an activator of ASK1/JNK signaling in breast cancer cells." (PMID 38678126, 2024). "Consequently, it was concluded that PDK4 inhibition might also drive ferroptosis dependent on autophagy in breast cancer cells." (PMID 38678126, 2024). "PDK4 could restrain cell proliferation and trigger cell apoptosis in lung and breast cancer." (PMID 37296697, 2023).
breast cancer (continued). "Besides this, PDK4 could contribute to the inhibition of cell proliferation and induction of apoptosis in lung and breast carcinoma." (PMID 34220962, 2021). "Furthermore, miR-16-5p overexpression improved TAMR sensitivity in breast cancer cells and cisplatin treatment sensitivity in osteosarcoma cells and participated in anti-adriamycin chemoresistance in cervical cancer through PDK4-mediated metabolic reprogramming." (PMID 36760722, 2023). "Upon cholesterol treatment, there is a significant increase in the expression of metabolic target genes of ERRα, including IDH3A, VEGF, PDK4, SOD2, GSTM1, and SPP1, in breast cancer cells." (PMID 32717915, 2020). "Similar to CD36, PDK4 and FABP4 are also highly expressed in CL breast cancers compared to all other molecular subtypes with the exception of normal-like breast tumours." (PMID 31942031, 2020). "We created a “fatty acid metabolism gene signature” consisting of CD36, LPL, PDK4, and FABP4 and checked each molecular subtype of breast cancer for upregulation or amplification of these genes." (PMID 31942031, 2020). "One study found that PDK4 can independently drive mitochondrial fragmentation in human embryonic kidney (HEK) cells, while another demonstrated that PDK4 inhibits autophagy in breast cancer cells." (PMID 40362448, 2025). "It is thus significant that cholesterol binding to ERRα and cholesterol-mediated increase in ERRα-PGC-1α interaction result in increased expression of ERRα itself and its metabolic target genes including IDH3A, VEGF, SOD2, GSTM1, PDK4, SPP1 in breast cancer cells." (PMID 32717915, 2020). "The data presented above point to altered regulation of pyruvate dehydrogenase as mediating breast cancer cell sensitivity to estrogen receptor ligands such as tamoxifen and ICI, and reveal an important role for the serine threonine kinase PDK4 in acquired SERM resistance." (PMID 26576332, 2015). "Furthermore, PDK4 knockdown activated ASK1/JNK pathway and ASK1 inhibitor (GS-4997) partially abrogated the impacts of PDK4 absence on the autophagy and ferroptosis in breast cancer cells." (PMID 38678126, 2024). "Here, our experimental results illustrated that LC3 and LC3B expression, LC3-II/I, ATG5 and ATG7 protein levels were increased, p62 expression and protein level were reduced after PDK4 was depleted in MCF-7 cells, suggesting that PDK4 interference might stimulate autophagy in breast cancer cells." (PMID 38678126, 2024). "As opposed to these studies, in mammary tumors from MMTV-PyMT+/−; Sirt6+/− mice and in MDA-MB-231 cells with silenced SIRT6, we did not detect increased PDK1 or PDK4 expression." (PMID 33482921, 2021). "Despite consistent correlation in expression between CD36, LPL, PDK4, and FABP4 in all breast cancer subtypes (data not shown), the only subtype that displayed poorer survival was CL-TNBC (p = 0.0119; HR = 1.92)." (PMID 31942031, 2020). "Unlike FBP1, we show that inhibition of PDK4 alone is sufficient to induce EMT, and ectopic expression of PDK4 could partially prevent TGFβ-induced EMT, although PDK4 is not differentially expressed between the basal and luminal subtypes of breast cancer (data not shown)." (PMID 25379179, 2014).
lung carcinoma (28 papers, 2013 to 2026). "Upregulated PDK4 expression is associated with various cancers including acute myeloid leukemia, lung cancer, laryngocarcinoma, ovarian cancer, and colon cancer." (PMID 32780563, 2020). "RESULTS: Eight PANoptosis-related genes (DAPK2, CAV1, PDK4, IL3RA, NOTCH1, CHMP4B, IRAK1, and SFN) were identified as being significantly associated with lung cancer." (PMID 41760846, 2026). "On the contrary, miR-182, by targeting pyruvate dehydrogenase kinase 4 (PDK4), has been described to promote lung cancer." (PMID 33050166, 2020). "A recent study reported that miR-182 plays regulatory roles in lung cancer metabolic pathways by targeting PDK4." (PMID 31597953, 2020). "In lung cancer cells, downregulation of PDK4 resulted in a shift from glycolysis to oxidative phosphorylation (OXPHOS)." (PMID 31822964, 2020). "In particular, in lung cancer cells the execution of the EMT program is accompanied by a downregulation of pyruvate dehydrogenase kinase 4 (PDK4) expression levels, which results in an increase of PDH activity." (PMID 28352611, 2017). "A recent study suggested increased reactive oxygen species via PDK4 expression and beta-oxidation of fatty acids as the likely anti-proliferative mechanism in lung cancer cells." (PMID 27401066, 2016). "A recent study characterized a PPARG anti-proliferative effect in lung cancer that was proposed to be due to the regulation of cellular reactive oxygen species via activation of pyruvate dehydrogenase kinase 4 (PDK4) and beta-oxidation of fatty acids." (PMID 27401066, 2016). "In contrast, in lung cancer cells decreasing PDK4 expression both prevented the antiproliferative action of a PPARγ agonist by blocking its action at the G1 → S phase checkpoint and promoted epithelial to mesenchymal transition and chemotherapy resistance." (PMID 26576332, 2015). "We observed dramatically decreased PDK4 in lung cancer biopsies compared to the corresponding normal tissue." (PMID 25379179, 2014). "In contrast, a tumor suppressive effect of PDK4 was observed in lung cancer and HCCa." (PMID 33384955, 2020). "Further, there has been provided in vivo evidence for a pyruvate dehydrogenase kinase 4 (PDK4)-dependent pathway activated by pioglitazone by which this PPARγ ligand increases the oxidative stress experienced by lung cancer cells, thereby ceasing their proliferation." (PMID 27164115, 2016). "In addition, analysis of human tumor samples revealed PDK4-low as a predictor of poor prognosis in lung cancer and that PDK4 expression is dramatically downregulated in most tumor types." (PMID 25379179, 2014). "Similarly, PDK4 was shown to enhance lipogenesis in lung cancer cells." (PMID 33384955, 2020). "Knockdown of PDK4 promotes growth of A549 and NCI-H1299 lung cancer cells, whereas overexpression of miR-182 reduces tumor growth via downregulation of PDK4." (PMID 36980540, 2023). "In lung cancer cells, TGF-β negatively regulates PDK4 expression and the downregulation of PDK4 leads to the transition from glycolysis to oxidative phosphorylation (OXPHOS)." (PMID 36059961, 2022). "TGFβ represses PDK4 expression, and PDK4 inhibition was sufficient to drive EMT and promote erlotinib resistance in epidermal growth factor receptor (EGFR) mutant lung cancer cells." (PMID 31822964, 2020). "Downregulation of PDK4 is sufficient to drive EMT and promotes erlotinib resistance in EGFR mutant lung cancer cells." (PMID 28352611, 2017). "We provide evidence that downregulation of PDK4 is responsible for such metabolic rewiring, is sufficient to drive EMT, and promotes erlotinib resistance in EGFR mutant lung cancer cells." (PMID 25379179, 2014). "Overexpression of PDK4 partially blocked TGFβ-induced EMT; conversely, PDK4 inhibition via RNAi-mediated knockdown was sufficient to drive EMT and promoted erlotinib resistance in EGFR mutant lung cancer cells." (PMID 25379179, 2014).
lung carcinoma (continued). "Accordingly, overexpression of PDK4 partially blocked transforming growth factor (TGF) β-induced EMT and, vice versa, PDK4 inhibition was sufficient to induce EMT and drug (erlotinib) resistance in lung cancer cells." (PMID 40801609, 2025). "PDK4 inhibition via RNA interference (RNAi)-mediated knockdown drove epithelial-mesenchymal transition (EMT) and promoted erlotinib resistance in EGFR mutant lung cancer cells 19, and siPDK4 in ovarian cancer cells promoted EMT and invasion but the effect was attenuated by PDK4 overexpression." (PMID 32489458, 2020).
hepatocellular carcinoma (22 papers, 2011 to 2026). A malignant tumor that arises from hepatocytes. "Downregulation of FLRT3 expression promotes an aggressive phenotype in colorectal cancer cells, and downregulation of PDK4 is associated with poor prognosis in hepatocellular carcinoma." (PMID 38358909, 2024). "TCDD dose-dependently induced Pdk4 and repressed Pdp2, while estrogen-related receptor γ (ERRγ) was induced which is associated with the induction of PDK4 in hepatoma cell lines under hypoxic conditions." (PMID 36914879, 2023). "These subgroups also exhibited differential expression of SFN and PDK4, which may contribute to a better understanding of the biology underlying hepatocellular carcinoma." (PMID 37398672, 2023). "GADD45G acts as a negative regulator of the Jak-Stat3 pathway and inhibits HCC by inducing cellular senescence; Deficient PDK4 expression promotes hepatocellular carcinoma cell proliferation, tumorigenicity, motility, and invasiveness." (PMID 40649911, 2025). "PDK4 was also found to be significantly downregulated in hepatocellular adenocarcinoma tissues; lower PDK4 levels in patients indicate lower overall survival rates and higher recurrence probability." (PMID 37296697, 2023). "A very recent work performed on human hepatocellular carcinoma identified PDK4 overexpression in spheres originated from cancer cells, featuring a defined stem-like phenotype." (PMID 31827705, 2019). "According to their claims, enhanced glycolysis is associated with CD133 ( +) stem-like features, and metabolic reprogramming with miR-122 or PDK4 may be a cutting-edge treatment option for hepatocellular carcinoma." (PMID 36803831, 2023). "Our findings suggest that enhanced glycolysis is associated with CD133 (+) stem-like characteristics and that metabolic reprogramming through miR-122 or PDK4 may represent a novel therapeutic approach for the treatment of hepatocellular cancer." (PMID 26506419, 2015). "To discover novel genes that modulate insulin sensitivity and HGP, we developed a high throughput human hepatoma-based G6PC/PDK4 gene expression assay and used it to screen a library containing synthetic small interference RNA (siRNAs) for 6650 genes encoding druggable protein targets." (PMID 22590537, 2012). "Genetic knockout of PDK4 in hepatocellular carcinoma (HCC) cells resulted in increased proliferation." (PMID 36980540, 2023). "A recent study confirmed the ability of DCA to revert PDK4-related chemoresistance also in human hepatocellular carcinoma (HCC)." (PMID 31827705, 2019). "Inhibition of PDK4 and LDHA markedly suppresses CD133 (+) stemness characteristics and overcome resistance to sorafenib (current chemotherapeutic agent for hepatocellular cancer)." (PMID 26506419, 2015). "Their results showed that blocking Pyruvate Dehydrogenase Kinase 4 (PDK4) and Lactate dehydrogenase A (LDHA) significantly reduced CD133 + stemness features and helped patients overcome sorafenib resistance (chemotherapy medication currently used for hepatocellular cancer)." (PMID 36803831, 2023). "Consistently, dual inhibition of LDHA, which blocks glycolysis end-step, and pyruvate dehydrogenase kinase 4 (PDK4), which favors the flow of pyruvate into the TCA cycle, represses the CSC phenotype in CD133+/PLC/PRF/5 hepatocellular carcinoma (HCC) cells." (PMID 33923958, 2021). "In the current study, hypoxia specifically increased PDK4 but not PDK2 in hepatoma cell lines." (PMID 23050013, 2012). "Extended further, VLDL stimulation of HL-expressing HUVECs and FAO hepatoma cells increased mRNA expression of canonical PPARδ target genes, including adipocyte differentiation related protein (ADRP), angiopoietin like protein 4 and pyruvate dehydrogenase kinase-4." (PMID 21750705, 2011).